IL21 (interleukin 21)
Diseases named in the same sentence as IL21 in open-access papers (continued):
Sharing a sentence is not in itself a finding about the gene and the disease.
chronic hepatitis B (16 papers, 2013 to 2023). "Serum IL-21 levels in patients with severe chronic hepatitis B (S-CHB), moderate chronic hepatitis B (M-CHB), and healthy controls (HC) were lower compared to HBV-ACLF patients." (PMID 36117587, 2022). "Studies have found that the ability of cTfh cells to produce IL-21 in response to hepatitis B surface antigen (HBsAg) during chronic hepatitis B virus infection is defective." (PMID 34782855, 2021). "Numbers of IL-21-producing CD8+CXCR5+ T cells are significantly increased in chronic hepatitis B (CHB)." (PMID 31663864, 2019). "In patients with chronic hepatitis B, circulating Tfh cells benefit hepatitis B e antigen seroconversion through IL-21." (PMID 27447555, 2016). "In a previous study, serum IL-21 levels in patients with chronic hepatitis B (CHB) and hepatitis B-related acute-on-chronic liver failure were significantly increased compared to levels in healthy controls." (PMID 27386263, 2016). "It was reported that circulating CXCR5+CD4+ T cells were expanded in patients with chronic hepatitis B and high frequency of circulating CXCR5+CD4+ T cells were associated with HBeAg seroconversion through IL-21 production manner." (PMID 27447555, 2016). "Mean serum IL-21 levels in patients with chronic hepatitis B (CHB) and the HCs were 303.54±152.77 pg/ml and 68.24±9.06 pg/ml, respectively (P=0.003)." (PMID 24669269, 2014). "Compared with the healthy controls, the plasma IL-21 level in chronic hepatitis B patients was significantly increased in chronic HBV carriers and decreased in inactive hepatitis B surface antigen (HBsAg) carriers (P<0.05)." (PMID 23407366, 2013). "Previous studies evidenced that serum IL-21 levels are elevated in chronic hepatitis B." (PMID 37875903, 2023). "In the field of hepatitis B virus (HBV)-related diseases, we found that HBV e antigen (HBeAg) seroconversion occurred in the antiviral therapy of chronic hepatitis B patients was closely related to IL-21, and the circulating CXCR5+CD4+ T cells benefit HBeAg seroconversion through IL-21." (PMID 28467480, 2017). "Therefore, IL-21 may drive chronic HBV infection from the IT phase into chronic hepatitis B phase by regulating the balance of Th17 and Treg cells and their functional mediators in chronic HBV infection." (PMID 37875903, 2023). "Therefore, IL-21 may play a crucial role in the progression from the IT phase to the chronic hepatitis B phase of chronic HBV infection." (PMID 37875903, 2023). "High levels of CXCL13 in patients with chronic hepatitis B stimulated the recruitment of CXCR5+ CD8+ T cells to produce high levels of HBV-specific interferon-γ and IL-21 in patients with chronic HBV infection to improve viral control." (PMID 35844446, 2022). "Significantly elevated levels of expression of IL21 and IL21R was observed in the livers of PBC patients, compared with those of chronic hepatitis B (CHB) patients, autoimmune liver hepatitis (AIH) patients or healthy controls (HC)." (PMID 28425483, 2017). "The frequency of Tfh cells, serum pro-inflammatory cytokine (IL-12, IL-21, IL-17 and TNF) levels and IgG/M levels were investigated in HBV-ACLF (n = 36), serious chronic hepatitis B (n = 21), moderate chronic hepatitis B patients (n = 32) and healthy control (HC) subjects (n = 10)." (PMID 33868273, 2021). "The TFH cell percentage, B cell percentage and IL-21 expression did not significantly differ between the hepatitis B e-antigen (HBeAg)− and HBeAg+ chronic hepatitis B groups (P>0.05)." (PMID 23407366, 2013). "Therefore, it is possible that lack of IL-12 or IL-21 results in low T-bet expression in chronic hepatitis B." (PMID 26809262, 2016). "Compared with chronic hepatitis B (CHB) patients infected with genotype B, higher levels of serum HBV DNA, ALT and TBil of patients infected with HBV genotype C may be related to their lower level of peripheral blood Tfh, which may result in lower IL-21, and it may result in lower HBV specific CTL." (PMID 23585765, 2013).
myeloma (16 papers, 2009 to 2025). "IL-21 was originally demonstrated to be a growth and survival factor in human myeloma cell lines, which is mediated through the activation of the JAK1/STAT3 signaling." (PMID 38720319, 2024). "IL-21 was originally demonstrated to be a growth and survival factor in human myeloma cell lines, which was mediated through the activation of JAK1/STAT3 signaling." (PMID 38720319, 2024). "In some haematological malignancies, such as multiple myeloma, Hodgkin's lymphoma and Burkitt lymphoma, IL-21 can induce the proliferation of neoplastic B cells." (PMID 32704112, 2020). "For example, IL-21 stimulation induces apoptosis of chronic lymphocytic leukemia and diffuse large B-cell lymphoma cells while promoting the growth of myeloma and waldenstrom macroglobulinemia tumor cells." (PMID 27176825, 2016). "A murine IL-21-secreting whole myeloma cell vaccine (mIL-21-Sp2/0) has also been used to prime immune responses against myeloma in vivo." (PMID 25961061, 2015). "The ability of IL-21 to sustain survival of normal PCs is reminiscent of the finding that IL-21 can promote growth and survival of malignant PC in multiple myeloma." (PMID 24600453, 2014). "Bcl-3 was induced in myeloma cell lines by interleukin (IL)-6, IL-21, IL-15, tumor necrosis factor-α and IGF-1, and its upregulation was associated with increased proliferation of the cells." (PMID 19191868, 2009). "Furthermore, NK cells expanded and activated by K562-OX40L-mb-IL-18/IL-21 feeder cells have shown cytotoxic activity against multiple myeloma in in vitro and xenograft mouse models." (PMID 36703992, 2022). "As IL-21 is also anti-apoptotic for myeloma cells, it is tempting to speculate that IL-21 could contribute to STAT3 activation in vivo in the setting of this malignancy." (PMID 24600453, 2014). "For example, IL-21-induced ERK1/2 phosphorylation has previously been demonstrated in monocytes, THP-1 AML cells, and multiple myeloma cell lines." (PMID 39536753, 2024). "PRL-3 expression was reported to be regulated at transcriptional level by mitogenic cytokines, such as IL-6, IL-21, HGF or IGF-1 in myeloma cell lines, or as TGF-β in colon cancer cell lines." (PMID 21466710, 2011). "The starting point of this study was our observation that IL-6, IL-21 and TNF-α induced expression of BCL3 in the myeloma cell lines OH-2 and IH-1." (PMID 19191868, 2009). "Microarray experiments done in our laboratory showed that the myeloma cell growth factors interleukin (IL)-6, IL-21 and tumor necrosis factor (TNF)-α all induced expression of the putative oncogene BCL3 in the myeloma cell lines IH-1 and OH-2 (paper in preparation)." (PMID 19191868, 2009).
glioma (15 papers, 2011 to 2025). A benign or malignant brain and spinal cord tumor that arises from glial cells (astrocytes, oligodendrocytes, ependymal cells). "In a mouse model of intracranially implanted gliomas, administration of IL-21 by stereotactic injections showed significant tumor rejection." (PMID 38638431, 2024). "Our group previously reported that VV armed with IL-21 exhibited effectiveness against tumors in murine PaCa, colorectal cancer, and glioma models." (PMID 39830516, 2024). "In a glioma GL261 model vaccinia virus expressing IL-21, VVΔTK-STCΔN1L-mIL-21, in combination with anti-PD1 antibody inhibited tumor growth leading to long-term survival for 80% of treated mice." (PMID 38638431, 2024). "Sun and colleagues studied an IL-21 vaccine virus, in combination with checkpoint inhibitors, in the treatment of glioma." (PMID 37759505, 2023). "Oncolytic vaccinia virus armed with interleukin-21 is an effective treatment in subcutaneous and orthotopic models of glioma and synergizes with α-PD1 to promote tumor clearance." (PMID 35795092, 2022). "Here, we used a new generation of VV expressing the therapeutic payload interleukin-21 to treat murine GL261 glioma models." (PMID 35795092, 2022). "Here, we demonstrate that a VV expressing IL-21, VVΔTK-STCΔN1L-mIL-21 is effective at evoking anti-tumor immunity and eliminating tumors after both i.t. and i.v. injection to glioma models." (PMID 35795092, 2022). "Glioma-associated DEGs CD244, IL21, RET, TGFA were up-regulated and AQP9, IGFBP2, EGFR, SOX9 were down-regulated specifically in the rat." (PMID 29352201, 2018). "Differently, in a murine model of glioblastoma, the use of a tumor cell vaccine producing IL-21, injected intracranially, prevented the subsequent growth of glioma tumors and cured most mice bearing early glioma implants." (PMID 25961061, 2015). "With this combined generality and accuracy, the model can potentially accommodate other clinical settings and solid cancers where similar immune processes apply and where IL-21 has been useful (i.e. adenocarcinoma, glioma, neuroblastoma)." (PMID 22022259, 2011). "We reported previously previously that a cytokine cocktail comprising IL-2, IL-15 and IL-21 selectively increases the population of central/effector memory tumor-reactive tumor-infiltrating lymphocytes (TIL) from pancreatic cancer as well as TIL from WHO grade 4 glioma after ex vivo expansion." (PMID 29854291, 2018). "Secreted factors such as leukotriene B4 (breast cancer), glioma cell-derived placental growth factor (glioma), TNF-α (tumor cells), and IL-21 (T cells), as well as cell contact-dependent mechanisms (CD40-CD40L and PD-1-PD-L1 axis,), promote cell differentiation Bregs in the TME." (PMID 37568713, 2023).
malaria (15 papers, 2014 to 2025). Malaria is a serious and sometimes fatal disease caused by a parasite that commonly infects a certain type of mosquito which feeds on humans. "Mice deficient in either IL-21 (Il21−/−) or IL-21R (Il21r−/−) were susceptible to rechallenge infections with homologous murine malaria parasites." (PMID 31867283, 2019). "CD4+ T follicular helper (Tfh) cells and their associated cytokines, such as IL-21, and germinal centre (GC) B-cells are critical mediators of humoral immune responses in many systems, and appear to be similarly important during experimental malaria." (PMID 27812214, 2016). "NK cells from malaria-naive individuals were also incubated with IL-15 and IL-21 for 6 days, where the proportion of IL-10 production is approximately 2%." (PMID 40337867, 2025). "We confirmed that malaria-specific IL-10/IFNγ co-producing cells also produce IL-21 using a flow cytometric assay." (PMID 37634385, 2023). "Collectively, data from these two reports support the idea that IL-6 and IL-21 play redundant roles in supporting Tfh cells during malaria, but are both independently important for supporting subsequent GC B cell responses." (PMID 36845571, 2021). "IL21 is critical to create parasite-specific B cell responses and disrupting IL21 signaling impairs protective humoral immunity to malaria." (PMID 34684226, 2021). "IL-21 is expressed in several murine malaria models, including P. berghei, Plasmodium chabaudi and Plasmodium yoelii." (PMID 31867283, 2019). "In one of the first reports on IL-21 induction in malaria, serum levels of IL-21, total parasite-specific IgG, and levels of IgG subclasses were measured in 73 Gabonese children positive for P. falciparum." (PMID 31867283, 2019). "IL-21 expression during human malaria has been mostly studied in the context of malaria infections caused by P. falciparum." (PMID 31867283, 2019). "For instance, studies have utilized P. berghei, a rodent malaria parasite, to analyze the extent to which the IL-21/IL-21R axis contributes to host immunity during CM in the murine hosts as a surrogate for the human disease." (PMID 31867283, 2019). "By purifying T and B cell subsets we demonstrated that circulating Tfh cells from malaria infected patients are the main source of IL-21 and trigger antibody production by naïve B cells." (PMID 28700710, 2017). "Purification of Tfh cells from malaria patients confirmed that these were the main source of IL-21 and therefore likely to play an important role in the induction of protective humoral immunity." (PMID 28700710, 2017). "Taken together, these findings suggest that IL-21 producing Tfh cells play an important role in the activation of B cells and antibody production during malaria." (PMID 28700710, 2017). "It is likely that mouse models of malaria will be informative for studies of cytokine-mediated effects on humoral immunity, as recently epitomized in studies of T cell-derived IL-21." (PMID 27812214, 2016). "IL-21-producing CD4+ T cells are present in peripheral blood mononuclear cells from malaria-exposed immune adults and correlate with P. falciparum-specific IgG antibodies in children with acute falciparum malaria." (PMID 25763578, 2015). "Our data uncover a mechanism by which CD4+ T cells and B cells control parasitemia during chronic erythrocytic-stage malaria through a single gene, Il21, and demonstrate the importance of this cytokine in the control of pathogens by humoral immune responses." (PMID 25763578, 2015). "While there is a predominantly Th1 cytokine profile in CD4 T cells in healthy rural African individuals who are exposed frequently to malaria, these T cells also express high levels of IL-10 and IL-21." (PMID 26646149, 2015). "It has been reported recently that PBMCs from malaria immune donors produced IL-21 and that increased plasma concentration of IL-21 correlated with Ag-specific IgG1 and IgG3 concentrations and." (PMID 24453249, 2014).
malaria (continued). "Following cytokine stimulation with IL-15 and IL-21, IL-10 release from NK cells was substantially greater from malaria-experienced individuals in both ADCC (~10-fold increase) and natural cytotoxicity assays (~5-fold increase) that occurred in the presence of IL-12." (PMID 40337867, 2025). "Additionally, we found that secretion of IL-10 by human malaria-naive NK cells is induced in vitro by cytokines IL-15, IL-21, and IL-12." (PMID 40337867, 2025). "First, Tfh cells have been observed to produce IFNγ alongside IL-21 during murine malaria." (PMID 36845571, 2021). "This highlights that IL-21 signalling in B cells is also crucial for optimal humoral immunity in malaria, in agreement with previous reports demonstrating the role of B cell-intrinsic IL-21 for plasma cell differentiation in vitro and GC B cell proliferation in vivo." (PMID 36845571, 2021). "Moreover, higher frequency of IL-21 producing Tfh cells was observed among acutely malaria patients when compared to HD." (PMID 28700710, 2017). "Since IL-21 levels and IgG responses were elevated during malaria, we sought to investigate whether P. vivax infection altered the proportions of circulating B cell subsets." (PMID 28700710, 2017). "Our data highlight, for the first time, the importance of IL-21-dependent B-cell responses in the acquisition of immunity to re-infection and suggest that long-lived B-cell responses are required to achieve immunity to malaria re-infection." (PMID 25763578, 2015). "However, when IL-21 is included during the 6 days of culture, followed by a short incubation with IL-12, we found significantly greater IL-10 secretion from NK cells from individuals naive to malaria (malaria-naive) and those with a history of malaria (malaria-experienced)." (PMID 40337867, 2025). "“Hybrid Th1/Tfh” or “Th1-like Tfh” have been used to describe any IFN-γ+ CD4 T cell also expressing IL-21 and/or CXCR5, functional markers of Tfh in Malaria models." (PMID 40356908, 2025). "CD4 T cells in adults from malaria-endemic areas also express cytokines of multiple lineages including IFN-γ, IL-10, and IL-21, even in cells with a Tfh-like phenotype." (PMID 32634740, 2020). "The PfGLURP- or PfMSP-3-elicited IL-21 production by PBMCs derived from P. falciparum-experienced human subjects may suggest potential roles for this cytokine to mediate immunity to P. falciparum infections and may further provide a surrogate biomarker to measure the efficacy of malaria vaccines." (PMID 31867283, 2019). "Here we show that IL-21 is produced by T follicular helper cells and co-expressed with IFN-γ during an erythrocytic-stage malaria infection of Plasmodium chabaudi in mice." (PMID 25763578, 2015). "Together, these findings suggest that a heterologous T helper memory cell population is critical to the malaria immune response because it maintains both cellular and humoral immunity through IFN-γ, IL-21, and CXCR5, and regulates pathology via IL-10." (PMID 26646149, 2015). "Here we have used a mouse model of malaria, Plasmodium chabaudi chabaudi AS in C57BL/6 mice, and have shown that IL-21 and Tfh cells are prominently induced and maintained in an erythrocytic-stage infection, suggesting that this crucial element of the humoral response is not impaired." (PMID 25763578, 2015). "Thus, T-bet+ B cells, even in the context of malaria, are likely to be a normal component of the immune compartment that becomes activated and expands, most probably in response to BCR, endosomal TLR, and IFNγ or IL-21 stimulation." (PMID 30387712, 2018).